CKMT1A (creatine kinase, mitochondrial 1A)
Diseases named in the same sentence as CKMT1A in open-access papers (continued):
Sharing a sentence is not in itself a finding about the gene and the disease.
cancer (continued). "Our findings provided a relatively comprehensive and intuitive map of CKMT1A for future research in cancer." (PMID 35705641, 2022). "Nonetheless, cancer cell detection by the expression of CKMT1A proved to be a more sensitive strategy for SW480 detection than USH1C, since down to 10 cells were efficiently detected." (PMID 34884994, 2021). "We also displayed the potential PTMs type and site of CKMT1A in cancer." (PMID 35705641, 2022). "Consequently, larger studies which have more sample sizes and more factors are required to confirm the role of CKMT1A in cancer." (PMID 35705641, 2022). "Accordingly, CKMT1A was found to be upregulated in EC patients with advanced stages of cancer." (PMID 35077462, 2022). "Emerging studies have shown that CKMT1A may participate in a series of cellular biological in the occurrence and development of human cancers such as cell proliferation, cell migration and apoptosis." (PMID 35705641, 2022). "Many new cancer therapeutic targets might be identified among the metabolic process in which CKMT1A is involved and cancer researches about them are needed in the future." (PMID 35705641, 2022). "Therefore, more studies on CKMT1A protein expression and experiment validation in cancers are needed." (PMID 35705641, 2022). "The genetic alteration of CKMT1A was explored across different cancer subtypes in TCGA dataset." (PMID 35705641, 2022). "Therefore, in this study, we used the TIMER, XCELL, QUANTISEQ, MCPCOUNTER, CIBERSORT, CIBERSORT-ABS and EPIC algorithms to investigate the correlation between the infiltration level of diverse immune cells and CKMT1A expression across various cancer types of TCGA in TIMER 2.0." (PMID 35705641, 2022). "Additionally, we categorized the 57 cancer cell lines from the Gboxin sensitivity screen into five groups based on their sensitivities, illustrating a positive correlation between the expression of CKMT1A, CKMT1B, and CKB and the cell's sensitivity to Gboxin treatment." (PMID 38896801, 2024). "The corresponding heatmap data also showed a positive correlation between CKMT1A and the top 10 correlated genes (excluded CKMT1B) in most cancer types." (PMID 35705641, 2022). "We combine a highly sensitive CTC capture assay exploiting the cancer cell binding recombinant malaria VAR2CSA protein (rVAR2) with the detection of colon-related mRNA transcripts (USH1C and CKMT1A)." (PMID 34884994, 2021). "A review of the literature revealed that aberrant expression of CKMT1A, GCNT1, NCALD, NFKBIB, NOMO3/Nodal, SLC16A5, or TRPV2 was correlated with cancer." (PMID 31363162, 2019). "We observed a statistically negative correlation between CKMT1A expression and the infiltration level of CAFs in most cancer." (PMID 35705641, 2022). "However, there is still a lack of systematic understanding of the contribution of CKMT1A in different types of cancer." (PMID 35705641, 2022). "While CKMT1A could potentially provide a more sensitive target for detection of rare cells in a WBC background, the analysis of healthy controls with no cancer cells spiked in revealed a considerable level of amplification within non-target cells." (PMID 34884994, 2021).
tumor (4 papers, 2015 to 2023). "As revealed by univariate analysis, tumor progression was associated with both high CKMT1A level [odds ratio; (OR = 3.459, P = 0.03)] and poor histological differentiation (OR = 0.144, P = 0.008)." (PMID 35077462, 2022). "Therefore, CKMT1A was regarded as a prognostic marker associated with tumor progression in EC patients." (PMID 35077462, 2022). "GO and GSEA were used to further assess the functions in the signaling pathways of CKMT1A in terms of promoting disease progression, and the role of CKMT1A within the tumor microenvironment was highlighted." (PMID 35077462, 2022). "Because some kinds of tumor types have no corresponding control tissues in TIMER2 database, we analyzed the expression difference of CKMT1A between normal and tumor tissues by using the normal tissue of the GTEx dataset as controls in GEPIA2." (PMID 35705641, 2022). "Then we used the “Similar Gene Detection” function of GEPIA2 to obtain the top 100 genes correlated with CKMT1A with all tumor expression data of TCGA included." (PMID 35705641, 2022). "Moreover, CKMT1A was upregulated in tumor tissues in TCGA (P = 0.005) and differentially expressed at different FIGO stages (P = 0.005)." (PMID 35077462, 2022). "The KEGG pathway suggested that “Glycolysis/Gluconeogenesis”, “Carbon metabolism”, “Biosynthesis of amino acids” and “metabolic pathways” might be involved in the effect of CKMT1A on tumor pathogenesis." (PMID 35705641, 2022). "A higher expression of CKMT1A contributed to tumor progression, which may contribute to unfavorable clinical outcomes." (PMID 35077462, 2022). "After systematic analyses, we found that the estimated infiltration value of CAFs was significantly negatively correlated with the expression of CKMT1A in most TCGA tumor types based on all or most algorithms, but not in LIHC." (PMID 35705641, 2022).
CKMT1A also shares sentences with these, for which no sentence is quoted: metabolic disease (2 papers); acute myeloid leukemia (1); colon cancer (1); gastric cancer (1); Glioblastoma multiforme (1); hearing loss (1); Huntington disease (1); infection (1); inflammatory bowel disease (1); lymph node metastasis (1); malignant glioma (1); pleural mesothelioma (1); prostate carcinoma (1); testicular germ cell tumor (1); Thyroid carcinoma (1); uterine carcinosarcoma (1).